PRL (prolactin)
Diseases named in the same sentence as PRL in open-access papers (continued):
Sharing a sentence is not in itself a finding about the gene and the disease.
tumor (continued). "It is the first choice for the treatment of prolactinomas, because it effectively reduces PRL secretion and shrinks tumours in most patients." (PMID 31000722, 2019). "We showed that MET inhibits the growth of GH3 and MMQ cells, as well as their xenografts, and provided evidence that MET significantly reduce PRL secretion of the two cells in vitro and in xenograft tumours." (PMID 30334324, 2018). "Surgery was also an option for case 5 which presented a normalized prolactin concentration, restored menstrual cycles, and disappearance of the tumor after the transsphenoidal surgery." (PMID 30542321, 2018). "Histologically, the tumor was classified as GH/PRL and sparsely-granulated type, with a Ki-67 labeling index < 1%." (PMID 29361932, 2018). "Molitch defined DA resistance as failure to achieve normal PRL levels or as failure to achieve a reduction in tumor size of at least 50% following treatment with maximal conventional doses of medication." (PMID 30407358, 2018). "The patient 6 was the one who normalized prolactin and the tumor disappeared after 17 years of treatment." (PMID 30542321, 2018). "Logistic regression analysis revealed that only tumor size [P = .007; OR (95% CI) = 5.748 (1.621–20.379)] and preoperative PRL levels [P = .006; OR (95% CI) = 3.866 (1.464–10.212)] were associated with unsatisfactory postoperative outcomes." (PMID 30407358, 2018). "Dopamine agonists are effective in reducing tumor size and controlling prolactin levels in 80–90% of microadenomas and about 70% of macroadenomas." (PMID 30171518, 2018). "Bromocriptine and cabergoline are effective to control prolactin concentrations and reduce the size of the tumor in most patients and are considered more effective than tumor surgery." (PMID 30542321, 2018). "We observed this phenomenon in patient 4 who only achieved control of prolactin concentration and a reduction in tumor size after transsphenoidal surgery." (PMID 30542321, 2018). "It decreased tumor size by inhibiting the synthesis and secretion of prolactin, and inhibiting angiogenesis in the surrounding tissue." (PMID 30349477, 2018). "Case 5 only achieved a normalized prolactin concentration (4.9 ng/mL) after surgical removal of the tumor." (PMID 30542321, 2018). "Both silent and functioning lactotroph tumors are sub-classified into sparsely granulated, demonstrating Golgi-like prolactin immunoreactivity and densely granulated with diffuse cytoplasmic expression of prolactin in the tumor cells." (PMID 29275530, 2018). "The abnormal secretion of PRL is related to many diseases, such as hyperprolactinemiaemia, tumor, and autoimmune diseases." (PMID 30210449, 2018). "One of the reasons for the discrepancies is the variable impact promoted by dopaminergic agonists regarding the reduction of prolactin concentrations and tumor volume." (PMID 30542321, 2018). "Bromocriptine reduces tumor growth by inhibiting synthesis and secretion of prolactin and inhibiting angiogenesis in the tumor environment." (PMID 30349477, 2018). "We used an animals model of fetal alcohol exposure that is known to promote tumor development and determined if alcohol programs the pituitary to acquire aggressive prolactin-secreting tumors." (PMID 29769550, 2018). "In patient 5, prolactin concentrations were controlled, and the tumor disappeared after transsphenoidal surgery." (PMID 30542321, 2018). "Another possibility is to normalize prolactin and shrink the tumor, but signs and symptoms persist, such as galactorrhea or menstrual changes." (PMID 30542321, 2018). "The down regulation of this metabolite, which is particularly emphasized in PRL-secreting PA, seems to be involved in tumor genesis." (PMID 30705668, 2018). "The excess of PRL secretion by the tumor can result in hypogonadism, infertility and galactorrhea, whereas tumor growth can lead to compressive mass effects resulting in headache and visual defects." (PMID 29464061, 2018).
tumor (continued). "Medical management of prolactinomas with BRC and CBG are typically first line treatment for the normalization of prolactin levels and restoring pituitary function and reducing tumor size." (PMID 30171518, 2018). "Treatment with cabergoline led to a 99.8% reduction in serum prolactin levels and significant tumor shrinkage." (PMID 30518416, 2018). "Even with the prolonged use of dopamine agonists, a reduction in tumor size only occurred after lengthy treatment, and normalization of prolactin concentration occurred in only one patient (case 6)." (PMID 30542321, 2018). "Bromocriptine normalizes prolactin and reduces tumor mass in 80–90% of patients with microadenomas and in 70% of patients with macroadenomas." (PMID 30349477, 2018). "Two patients achieved control with cabergoline monotherapy, one with moderately elevated IGF-I (1.3 × ULN) and the other with a GH/PRL-secreting tumor, supporting prior data that these factors likely influence response to DA therapy." (PMID 30186234, 2018). "In clinical practice, dopamine agonists (DAs) are recommended as first-line therapy for patients with prolactinomas to control tumor volume, normalize PRL secretion, alleviate neurologic symptoms and restore normal functions of pituitary." (PMID 30410470, 2018). "MET + BC further decreased tumour growth and serum PRL levels in xenografts than BC treatment alone." (PMID 30334324, 2018). "She currently attends regular follow-up visits, with normal PRL levels and significant tumor shrinkage during this 3-year follow-up period." (PMID 30518416, 2018). "According to a review by Oh and Aghi, dopamine agonists reduce the size of prolactinomas and the concentration of prolactin through binding to the dopamine D2 receptor in the tumor cells." (PMID 30542321, 2018). "A high prolactin concentration was maintained using this dose for 4 years; however, images showed a marked decrease in the tumor size." (PMID 30542321, 2018). "There is an argument for annual prolactin levels and repeat imaging only if there is a marked increase in prolactin (> 250 μg/L) or clinical signs of tumour expansion." (PMID 30014342, 2018). "It has been concluded that EG-VEGF and prolactin have a synergistic effect on the proliferation rate of tumor cells and that it is involved in tumor growth." (PMID 28386275, 2017). "MEN1/Menin was originally discovered for its tumor suppression function in the pituitary (anterior lobe) and pancreatic islets, which are well-known endocrine organs that secrete prolactin and insulin, respectively." (PMID 28710500, 2017). "PRL has been recently proposed to impair the tumor-suppressive function of BRCA1 by downregulating expression of the cell cycle inhibitor p21 in cancer cell lines." (PMID 28966800, 2017). "In the current study, we have determined that upregulation of miR-106b by prolactin likely contributes to tumor malignancy." (PMID 28422740, 2017). "GH3 cells are of rat origin and are currently the most commonly used in vitro model of functional secreting tumours since they secrete both growth hormone and prolactin." (PMID 28649092, 2017). "One patient (1 PRL) showed an initial TMZ response but tumor growth reoccurred while still receiving TMZ." (PMID 28900805, 2017). "Under these latter conditions, PRL crosstalk with estrogen increases alignment of the matrix perpendicular to the tumor edge, similar to that correlated with decreased survival of patients with ERα + tumors." (PMID 28103936, 2017). "DAs are a first-line therapy for IGPs because they can effectively achieve long-term control in both shrinking tumor volume and normalizing the PRL level, and majority of patients need low-dose DA maintenance." (PMID 27999593, 2016). "From their findings, PRL interacted with short form PRLR to constrain tumor promoting liver inflammation." (PMID 27102295, 2016). "Radiotherapy aims to slow or stop tumor growth, restore normal prolactin levels, and minimize radiation dose toxicity." (PMID 27489751, 2016).
tumor (continued). "In contrast, the superiority of cabergoline in terms of patient tolerability and convenience, reduction in prolactin secretion, restoration of gonadal function, and decrease in tumor volume has been convincingly demonstrated." (PMID 27999593, 2016). "Most genes in the axonal guidance signaling pathway showed a hypermethylation effect in tumor tissue; while most in the prolactin signaling pathway and glycosphingolipid pathway showed hypomethylation." (PMID 27090937, 2016). "In this retrospective study, in 90% of patients with microadenomas whose treatment with DA was stopped during menopause experienced tumor reduction in size and maintained PRL levels within the normal range." (PMID 26909481, 2016). "These pharmacologic approaches are effective, reducing serum prolactin levels by nearly 50% in nearly all patients and the size of the tumor by greater than 25% in the vast majority of patients." (PMID 27489751, 2016). "Similar to GH, PRL has been reported to function as a tumor promoter for chemically initiated rat liver cells." (PMID 27102295, 2016). "The response to these drugs varies; approximately 95% of patients treated with standard doses reach normal PRL levels with the tumor decreasing in size or disappearing." (PMID 26909481, 2016). "Dopamine agonists have been demonstrated as a first-line therapy for IGPs, because they can significantly shrink tumor volume and control the PRL levels." (PMID 27999593, 2016). "DAs as first-line therapy can effectively achieve long-term control in both shrinking tumor volume and normalizing PRL levels." (PMID 27999593, 2016). "In our study, tumor volume shrank by a mean of 98.6% and the incidence of PRL normalization was 76%." (PMID 27999593, 2016). "In prolactinomas there is a close relation between PRL levels and the tumor size; the bigger the tumor is, the higher the PRL levels are." (PMID 26909481, 2016). "Although the tumor volume almost disappeared, the PRL levels continued to exceed 200 ng/mL during the long-term followup period." (PMID 27999593, 2016). "Prolactin was elevated to 51 ug/L (normal male 4–15 ug/L) due to the tumour stalk effect (i.e. mass effect from the tumour on the pituitary infundibulum)." (PMID 27069570, 2016). "The aim was to assess the evolution of tumor size and prolactin (PRL) levels in patients with micro and macroprolactinomas diagnosed and treated with dopamine agonists during fertile age, and the effects of suspension of drugs after menopause." (PMID 26909481, 2016). "The patient was referred to an endocrinologist and began dopamine agonist (cabergoline) therapy given his prolactin level and residual tumor." (PMID 26885420, 2016). "Dopamine agonists (DAs) have been increasingly used as a treatment of choice for prolactinomas as it normalizes prolactin levels and leads to tumor shrinkage." (PMID 26074878, 2015). "Pharmacological intervention is the first-line treatment and involves the use of dopamine agonists (DAs) to reduce tumor size and prolactin level." (PMID 25884948, 2015). "They effectively suppress prolactin (PRL) hypersecretion, reduce tumor size, and restore gonadal function." (PMID 26513171, 2015). "Further administration of PRL enhanced tumor growth, whereas pharmacological suppression of PRL secretion inhibited DMBA-induced mammary carcinogenesis in the rat." (PMID 26691922, 2015). "Cabergoline is more expensive but is more effective in normalizing prolactin (PRL) levels and in reducing tumor size." (PMID 25737721, 2015). "Cabergoline (CAB), the first-line drug for treatment of prolactinomas, is effective in suppressing prolactin hypersecretion, reducing tumor size, and restoring gonadal function." (PMID 26513171, 2015). "Normal serum prolactin levels were found in tumor-bearing rats confirming that GC tumors produce exclusively GH." (PMID 26549306, 2015).
tumor (continued). "According to previous studies, predictor factors for higher chance of successful CAB withdrawn include lower PRL levels, longer duration of treatment, tumor size (micro- > macroadenomas), previous pituitary radiotherapy or surgery, and pregnancy." (PMID 25699020, 2015). "In this cohort, 74 % of patients (56/76) normalized PRL following DA treatment and tumor shrinkage was achieved in 76 % (56/74) of patients, with a median CAB dose of 1.5 mg/week." (PMID 28702224, 2015). "In those instances where use of DA has altered tumor morphology, therapeutic efficacy is commonly signaled by tumor involution and/or decline in serum PRL level, plus diminished PRL immunoreactivity (especially in the small cells that populate prolactinomas)." (PMID 26228535, 2015). "A dopamine agonist (DA) (bromocriptine or cabergoline) is the treatment of choice that can normalize prolactin levels, reduce tumor size, and restore ovulation and fertility." (PMID 26074878, 2015). "PRDM2 showed a synergistic effect with BRC on the inhibition of prolactin (PRL) secretion and MMQ cell viability, and low PRDM2 expression was associated with tumor recurrence." (PMID 25884948, 2015). "Our data strongly suggests that plasma prolactin significantly correlates with CRC tumour progression through Dukes’ stage A, B and C, being continuously upregulated until distal metastasis occurs." (PMID 25987887, 2015). "Diagnostically, PRL gradually increases throughout pregnancy and cannot be used for the estimation of tumor size dynamics." (PMID 28702224, 2015). "Apart from PRL normalization and hormone secretion recovery, tumor shrinkage to relieve tumor mass effects and prevent neurological complications is another treatment goal for patients harboring macroprolactinomas." (PMID 28702224, 2015). "The hardened elastic quality of the tumor and its strong attachments to neighboring structures prevented complete removal, but related mass effect was significantly reduced and serum PRL level declined (to 250 ng/ml) in steps at each procedural stage." (PMID 26228535, 2015). "The aim of medical therapy for prolactinoma is to reduce the volume of the tumor and decrease the level of PRL to improve the endocrine symptoms." (PMID 24669252, 2014). "In breast and prostate cancers, where local PRL production has been demonstrated, its proliferative potential via an autocrine/paracrine mechanisms has been proposed to contribute to tumor development and progression." (PMID 24859278, 2014). "The serum prolactin concentration, tumor size, and clinical characteristics were statistically compared." (PMID 25142896, 2014). "Nine months after radiotherapy, the serum prolactin had fallen to 621 mIU/l (29.29 ng/ml), and an MRI after 12 months showed a reduction in tumour volume." (PMID 25520847, 2014). "Tumor recurrence was significantly less frequent in the CD group (4 patients, 8.3%) than in the CD + PRL group (13 patients; 36.1%) (P < 0.001)." (PMID 25506361, 2014). "The patient had a striking response to pharmacological treatment with combined SSA and dopamine agonist therapy in terms of GH/IGF-1 and prolactin normalization, as well as reduction in tumor volume." (PMID 24166706, 2014). "Weak to moderate nuclear Gαi-3 staining was also observed in all tumor types (GH: 1.3±0.8, PRL: 0.8±0.5, ACTH: 1.3±0.6, NFPA: 1.5±0.6)." (PMID 25291362, 2014). "All tumor types displayed moderate cytoplasmic expression of Gαi-3 (GH: 2.3±0.5, PRL: 2±0.8, ACTH: 1.6±0.6, NFPA: 1.8±0.5)." (PMID 25291362, 2014). "Hormone therapy with dopamine agonists (for PRL-producing tumours) and somatostatin analogs (for GH-producing tumours) are used to control the biochemical secretions." (PMID 24520294, 2014). "In lactotrope hyperplasia induced by a synthetic estrogen, treatment with ABT-510 and ABT-898, two thrombospondin analogs with antiangiogenic properties, counteracted pituitary size and serum prolactin increase, and decreased tumor vasculature." (PMID 25505910, 2014).
tumor (continued). "Extrasellar tumor growth, mixed tumors (GH- and prolactin-secreting), dural invasion, tumor size, cavernous sinus invasion, Knosp grade, and pre-operative GH and IGF-1 levels have all been shown to be predictors of poor surgical outcome." (PMID 24293348, 2014). "In every patient in the CD + PRL group, a mixed tumor with ACTH- and PRL-positive cells was discovered by pathological investigations following surgery." (PMID 25506361, 2014). "Further dose titrations were required as the prolactin level plateaued and significant residual tumour remained." (PMID 25520847, 2014). "Anti-VEGF strategies resulted in prolactin inhibition and decreased tumor cell proliferation in these mice." (PMID 25136513, 2014). "Giant prolactinomas (tumor volume exceeding 4 cm in diameter and/or with prolactin levels higher than 3000 ng/mL and mass effect), a rare subcategory of macroprolactinomas, remain one of the greatest challenges in neurosurgery." (PMID 25505910, 2014). "In the present study, the size of the tumor increased rapidly in the latter half of the gestation and lactation periods, and the levels of estrogen and prolactin were high." (PMID 25364429, 2014). "No testosterone replacement was initiated, in anticipation of further tumor response to DA therapy and subsequently normalization of both the prolactin level and spontaneous puberty." (PMID 25165538, 2014). "Local therapy with VEGF-TRAP or a systemic treatment with a monoclonal antibody targeting murine VEGF resulted in substantial tumor and prolactin inhibition in hyperplastic pituitaries from Drd2−/− female mice." (PMID 25505910, 2014). "Nine months after treatment the serum prolactin had fallen to 621 mIU/l, and 12 months after an MRI showed reduced tumour volume." (PMID 25520847, 2014). "In fact, T47D xenotransplant tumor regions expressing high GLUT1 were resistant to exogenous prolactin despite retaining prolactin receptor and Stat5 expression." (PMID 24004716, 2013). "T47D xenografts were established in nude mice and mice were exposed to human PRL or saline for 48 h before RNA isolation from tumor extracts." (PMID 23758962, 2013). "Normalisation of prolactin levels soon after surgical removal of the tumour, positive immunohistochemistry for prolactin and normal pituitary gland on imaging strongly support the diagnosis." (PMID 24616762, 2013). "Beside inhibition of prolactin secretion it is also known for reduction of tumor cell mass and inhibition of transcription, furthermore necrotic effects have been detected." (PMID 23969837, 2013). "The most accredited theory proposed a simpler mechanism for THs effects on estrogen responses through the increase in αERs with resultant increase in PRs, prolactin production and tumor growth." (PMID 24058909, 2013). "The GH-secreting nature of the ectopic tumor was documented by immunohistochemistry in 12 of the reported cases; in six, there was concomitant, PRL immunostaining." (PMID 24119925, 2013). "In T47D cells, PRL also blocked progestin-induction of a tumor-initiating CK5-positive cell population through a mechanism that involved PRL-suppression of progestin-induced BCL6." (PMID 23758962, 2013). "Of those, we considered prolactin and its receptor appeared as the most interesting candidate genes, since this pathway has been reported to be involved in the progression of several tumor type." (PMID 24257371, 2013). "Prolactin induces upregulation of NCR expression augmenting NK cytotoxicity against tumour cells, and vice versa corticosteroids or TGF-β1 reduces NK cytotoxicity." (PMID 23476104, 2013). "Tumor-bearing nude mice received either human prolactin (N = 10) or vehicle (N = 10) subcutaneously every 12 h for 48 h." (PMID 23758962, 2013). "Studies in the rat model had shown that prolactin promoted HCC progression while prolactin inhibition led to reduced tumor growth and longer latency." (PMID 23874805, 2013).